FAM120AOS (family with sequence similarity 120 member A opposite strand)
Synonyms: C9orf10OS
Tractability: No criterion of Open Targets' tractability assessment is met for any kind of drug.
Gene: Protein-coding gene on chromosome 9 (93,431,441 to 93,453,581, reverse strand). Ensembl gene ENSG00000188938.
Gene Ontology:
Molecular function: protein binding
Genetic constraint (gnomAD): Loss-of-function variants: 15 observed, 19.65 expected, observed/expected ratio (o/e) 0.76, 90% interval 0.51 to 1.18. The upper end of that interval is the gene's LOEUF score, 1.18, which puts it in group 5 of 6, group 1 being the genes least tolerant of losing a copy. Missense variants: 318 observed, 329.15 expected, observed/expected ratio (o/e) 0.97, 90% interval 0.88 to 1.06. Synonymous variants: 149 observed, 138.98 expected, observed/expected ratio (o/e) 1.07, 90% interval 0.94 to 1.23.
Homologues: Orthologues: chimpanzee FAM120AOS (99% identical), macaque FAM120AOS (94% identical).
Diseases named in the same sentence as FAM120AOS in open-access papers:
FAM120AOS is named in the same sentence as 6 diseases in open-access papers, as found by Europe PMC text mining. Sharing a sentence is not in itself a finding about the gene and the disease. The quoted sentences say what the papers report.
HIV-1 infection (1 paper, 2021). The type species of lentivirus and the etiologic agent of acquired immunodeficiency syndrome (AIDS). "Interestingly, FAM120AOS was suggested to be able to regulate the expression of ITGB1 (CD29), whereas ITGB1 has already been reported to be correlated with HIV-1 infection." (PMID 35004856, 2021).
tumor (2 papers, 2020 to 2022). "In vitro studies revealed that four selected lncRNAs including, CDKN2B-AS1, LOC102724156, HAGLR and FAM120AOS were significantly increased in the presence of in optimum concentration of Ag@Glu/TSC and decreased in tumor tissues versus adjacent normal tissues." (PMID 33292233, 2020).
FAM120AOS also shares sentences with these, for which no sentence is quoted: Anxiety (1 paper); cancer (1); Intellectual disability (1); Obesity (1).